CCR7 (C-C motif chemokine receptor 7)
Diseases named in the same sentence as CCR7 in open-access papers (continued):
Sharing a sentence is not in itself a finding about the gene and the disease.
tumor (continued). "The mesenchymal phenotype is maintained via TGF-β1 expression in both tumor cells and immune cells in the tumor microenvironment, and is supported by CCR7, which drives lymph node metastasis and a poorer OS among patients strongly expressing CCR7." (PMID 26176983, 2015). "Of note, the level of CCR7 mRNA in tumor tissues was significantly higher than that in the control samples." (PMID 25744065, 2015). "The immunostaining showed that CCR7 was mainly detected on the membrane and in the cytoplasm of tumor cells." (PMID 26667143, 2015). "Research has revealed that the Akt and ERK pathways are involved in the CCR7-induced migration of tumor cells, and we also detected increased activation of ERK1/2 and p-Akt in KYSE410 and Eca9706 cells after treatment with CCL21." (PMID 26667143, 2015). "In vivo studies revealed that metastatic tumor formation is decreased when CCL21 expression is knocked down in secondary lymphoid organs, since this diminishes both the chemotactic and antiapoptotic effects of CCR7-expressing tumor cells." (PMID 25744065, 2015). "Double immunostaining also revealed higher levels of TGF-β1 in the cytoplasm of tumor cells in CCR7-high GC samples." (PMID 26176983, 2015). "To further explore the CCR7-related mechanism in tumor metastasis, we applied bioinformatic methods previously proven useful for identifying target genes or proteins." (PMID 26176983, 2015). "As a chemokine receptor, CCR7 has been proven to be involved in lymphatic metastasis in various cancers, including ESCC, and the role of the CCL21-CCR7 axis in inducing the directional migration and invasion of tumor cells has also been proven." (PMID 26667143, 2015). "The involvement of CCL21/CCR7 pair in migration and guidance of the cells detached from the primary tumor towards draining lymphatics is believed to play a significant role in the subsequent metastatic evolution of the disease." (PMID 25744065, 2015). "While exogenous CCL21 has stimulated VEGF-C production by parental cells, the secretion level of VEGF-C from CCR7 shRNA transfected tumor cells has decreased significantly." (PMID 25744065, 2015). "To further explore the contribution of CCR7 to the invasiveness of tumor cells, we next examined its effect on MGC80-3 and SGC-7901 cell migration in transwell invasion assays." (PMID 26176983, 2015). "Tumor-infiltrating T cells are predominantly antigen experienced CD45− CCR7− effector/memory T cells (74.7% of CD45+CD3+ lymphocytic cells in tumor tissue compared to 30.2% and 26% in PBMCs of CRC patients and healthy controls respectively, p<0, 005)." (PMID 25026291, 2014). "Many studies show that primary tumor cells and metastatic cells express CCR7 in the draining lymph node and that there is a significant correlation between lymph node metastasis and CCR7 expression in many tumor entities." (PMID 25254213, 2014). "In this regard, it is noteworthy that prior studies characterized CCR7 and heparan sulfate as co-receptors for CCL21 accumulation on hLECs and important for recruitment of CCR7-expressing tumor cells." (PMID 24489642, 2014). "A clinical study showed that high tumor infiltration by cytotoxic CD8+ T cells expressing CCR7 had a favorable prognostic value in colon cancer patients." (PMID 24810425, 2014). "The role of CCL21/CCR7 axis in tumor immunity has been closely investigated in the past two decades." (PMID 24810425, 2014). "For example, in lung cancer, hypoxia induces the expression of CCR7 by tumor cells that increases cell invasiveness and eventual lymph node metastasis." (PMID 25110692, 2014). "In contrast, patients whose tumor tissue presents a combined low infiltration score for both of CCR7+ and regulatory lymphocyte cell populations had a very poor outcome." (PMID 24810425, 2014). "Obstructing CCR7 expression at mRNA level in a murine tumor model inhibited lymph node metastasis and lymphangiogenesis." (PMID 25254213, 2014).
tumor (continued). "Chemokines have been shown to be involved in tumor lymphangiogenesis and metastasis; for example, VEGF-C upregulated chemokine ligand 21 (CCL21) on lymphatic endothelium, whereby CCR7 expressing tumor cells were attracted towards the lymphatic vessels." (PMID 25254213, 2014). "At the same time, we found the increased level of CCR7 at tumor sites in both the SLC group and combination therapy group, concordant with the chemotactic properties of SLC." (PMID 24304581, 2013). "In contrast, other studies indicate that the CCL21/CCR7 pathway promotes increased tumor control as a result of increased recruitment of effector immune cells." (PMID 23874342, 2013). "In contrast, the treatment with the anti-human CCR7 mAb significantly delayed the tumor appearance and the first subcutaneous tumors were observed at day 17 in three out of five mice (day 17)." (PMID 24305507, 2013). "The assumption is sustained by the observation that CCR7− CAR T cells persist in higher numbers in the tumor lesion although both the CCR7+ and CCR7− subset T cells equally efficiently target to the tumor." (PMID 23761793, 2013). "The C–C chemokine receptor-7 (CCR7) is a G protein coupled receptor that has a role in leukocyte homing, but that is also expressed in aggressive tumor cells." (PMID 24068998, 2013). "In accordance with previous studies conducted on other types of cancer, the staining for CCR7 was localized in the membrane and cytoplasm of the tumor cells, while VEGF-C was predominantly cytoplasmic." (PMID 23761820, 2013). "To further explore the contribution of this chemokine axis in tumor eradication mediated by Val-boroPro, we created CCR7−/− bone marrow chimeras reconstituted with CCR7-expressing wildtype T cells to exclude T cell trafficking effects." (PMID 23554941, 2013). "The cells of squamous cell carcinoma of head and neck secrete the chemokines CCL19 and CCL21, which leads to the activation of CCR7 and promotes tumor growth and progression." (PMID 24259307, 2013). "The anti-CCR7 therapy significantly delayed the tumor appearance and also reduced the volumes of tumors in the subcutaneous model." (PMID 24305507, 2013). "In the process of tumor occurrence and development, CCR7 on the tumor cell surface binding to its ligand SLC can promote tumor cell proliferation, angiogenesis in the tumor tissue, and directional migration." (PMID 24040244, 2013). "Inhibition of tumor growth was associated with reduced frequencies of Tregs and MDSC but enhanced recruitment of CCR7+Foxp3− T cells." (PMID 23874342, 2013). "Paradoxically, the anti-tumor response of CCR7− CAR T cells is less efficient than that of CCR7+ T cells when redirected by a CD28-ζ CAR." (PMID 23761793, 2013). "Tumor growth inhibition was evident until day 17 in the mice treated with anti-CCR7 mAb, even though treatment was stopped at day 10 post-inoculation." (PMID 24305507, 2013). "The correlation between CCR7 expression and lymph node metastasis of tumor cells was further approved in animal studies." (PMID 23667660, 2013). "Tumor cell chemotaxis mediated by CCR7 signaling is well documented and explains the metastatic homing to lymph nodes." (PMID 24068998, 2013). "The process is observed in a mouse tumor model in which after adoptive transfer of young CCR7+ CAR T cells the majority of tumor infiltrating CAR T cells are of CCR7low phenotype." (PMID 23761793, 2013). "We also co-transferred CCR7 (+/+) and CCR7 (−/−) FoxP3+ T cells for competitive population in tumor-bearing scurfy mice." (PMID 22292042, 2012). "Conversely, molecules proposed to be direct mediators of lymphatic colonization include CCL21 and SDF-1 interacting with their tumor-expressed receptors, CCR7 and CXCR4, respectively." (PMID 22295241, 2012). "The presence of CCR7 on tumor cells and the accumulated evidence suggesting their involvement in LN metastasis is an appropriate segue way to a discussion of the role of tumor-induced lymphangiogenesis in LN metastasis." (PMID 24212647, 2011).
tumor (continued). "This study further concluded from additional in vitro and orthotopic mouse model studies that blockage of CCR7 impaired tumor cell proliferation and decreased resistance to cisplatin-induced apoptosis." (PMID 24212639, 2011). "CCR7-expressing stromal cells had the same morphology and distribution in the primary tumor and in the invaded lymph nodes." (PMID 21624121, 2011). "In contrast, CCR7+/α-SMA+ stromal cells were observed in 34 of 85 tumor-invaded LN, most often in the "histiocytic" areas of the lymph node, in or beneath the sub-capsular sinus." (PMID 21624121, 2011). "When limited numbers of tumor cells were inoculated into murine skin, overexpression of CCR7 directly facilitated primary tumor formation." (PMID 24212647, 2011). "It should be considered that peripheral CD8+ T cells expressing effector functions against viral or tumor antigens are almost uniformly CCR7- and are endowed with full effector capacities, far greater than naïve or TCM cells." (PMID 22112244, 2011). "High CCR7 expression in T-NHL cells is significantly associated with lymphatic and distant dissemination as well as with tumor cell migration and invasion in vitro." (PMID 21548969, 2011). "Migration of metastatic tumor cells from the bloodstream into lymph nodes is thought to be facilitated by expression of the chemokine receptors CCR7, CXCR4 and, for B cell-derived tumors, CXCR5." (PMID 21672222, 2011). "Our results reveal that high CCR7 expression significantly influences lymphatic and hematogenous tumor dissemination, and also correlates with clinical staging." (PMID 21548969, 2011). "In the regional axillary lymph nodes, CCR7+ myofibroblasts are therefore observed only in case of nodal involvement by tumor cells and only from primary tumors containing CCR7-expressing stromal cells." (PMID 21624121, 2011). "The functional role of CCR7 in tumor metastasis was studied by implanting B16 tumor cells that were transduced with CCR7 or empty vectors in mouse footpads." (PMID 24212647, 2011). "One notable difference was that CCR7 expression correlated to cases with advanced tumor stage, while CXCR4 was significantly higher in patients with distant metastases." (PMID 24212639, 2011). "The migration of these two CCR7 expressing cell lines was significantly stimulated by CCL21, implying an important role and intact function of CCR7 during tumor progression." (PMID 21548969, 2011). "DCs were evaluated for antigen uptake, and following maturation with LPS and IFN-gamma, DCs were assessed for expression of CD80, CD40, CD86, ICAM-1 and CCR7, production of IL-12p70 and IP-10, and induction of tumor-specific T-cell responses." (PMID 22194898, 2011). "The expression of chemokine receptors CCR7 has been studied in relation to tumor dissemination and poor prognosis in a limited number of cancers." (PMID 21548969, 2011). "Conversely, MIP-3β and SLC expression was only detected at the tumour border, where CCR7-expressing T-cells and mature DCs formed clusters." (PMID 20969772, 2010). "CXCR4 and CCR7 expression is significantly higher in patients with larger tumor size, deep stromal invasion, lymph-vascular space involvement, or lymph node metastasis." (PMID 20049170, 2010). "Lymphatic heparan sulfate was also required for binding of CCL21 to its receptor CCR7 on tumor cells as well as the activation of migration signaling pathways in tumor cells exposed to lymphatic conditioned medium." (PMID 21172016, 2010). "Expression of these chemokines favours homing and interaction of CCR7-expressing cells, such as mature myeloid DCs and naïve or memory T cells, facilitating their interaction for an optimal anti-tumour immune response." (PMID 20969772, 2010). "Together with their CXCL12 and CCL21 ligands, CXCR4 and CCR7 were significantly highly expressed in tumor cells with lymph node (LN) metastasis." (PMID 20181250, 2010).
tumor (continued). "Importantly, we questioned whether these signaling alterations on tumor cells that depend on the state of HS in the conditioned medium were associated with "upstream" alterations in the ability of CCL21 to associate with CCR7 G-protein coupled receptors on tumor cells." (PMID 21172016, 2010). "Patients with primary tumours that displayed high-level (‘++’ or ‘+++’) immunostaining for CCR7 had significantly worse overall and disease-specific survival rates than patients with low level (‘−’ or ‘+’) immunostaining (respectively)." (PMID 17687340, 2007). "Fifteen percent of patients with the highest level of tumour CCR7 immunopositivity relapsed with systemic metastases." (PMID 17687340, 2007). "Relapse-free (P=0.0175), overall (P=0.0136) and disease-specific (P=0.0062) survival rates were significantly lower in patients whose tumours expressed high levels of CCR7." (PMID 17687340, 2007). "Twelve patients with high-level CCR7 expression in the primary tumour presented with N0 or N1 disease but went on to develop disease relapse." (PMID 17687340, 2007). "Analysis of CCR7 immunostaining in the primary tumour with respect to subsequent disease relapse demonstrated a nonsignificant trend (P=0.096)." (PMID 17687340, 2007). "In summary, in this study we have shown a strong correlation between CCR7 immunostaining in the primary tumour and the presence of synchronous cervical nodal metastasis." (PMID 17687340, 2007). "The expectation was that the percent of CD4+CD25+CCR7+ cells would be lower in patients than NC, based on our report documenting an enrichment in Treg at tumour sites and tumour-involved lymph nodes relative to the peripheral circulation." (PMID 15714205, 2005). "Furthermore, in tumor tissues, naïve T-cells exhibited higher expression levels of CCR7, whereas, in normal tissues, naïve T-cells displayed increased CD69 expression." (PMID 41186645, 2026). "Primed CAR-NK cells showed increased CCR7 expression and improved tumor-directed migration." (PMID 42305549, 2026). "Although we demonstrated that blocking CCR7 signal on tumor cells enhanced the sorafenib sensitivity of HCC, which was mediated by inhibiting the EMT process and leaded to the tumor suppression, the mechanisms behind these changes remain unclear." (PMID 40685403, 2025). "To detect CCR7 expression in mesenchymal sites, we observed the samples under different magnifications and were able to clearly identify the mesenchymal sites of the tumor tissues (outlined with dashed lines and separated from the tumor sites)." (PMID 40685403, 2025). "To test this hypothesis, we monitored phenotypic changes in CD19 CAR-T cells, specifically examining the expression of CD45RA and CCR7 using flow cytometry across three sequential tumor rechallenges." (PMID 39891728, 2025). "In addition, some CCR7+ cDC1s remain in the tumour and express immunoregulatory molecules including programmed death ligand 1 (PD‐L1), suppressing anti‐tumour CD8+ T cell activity via PD‐1." (PMID 40878038, 2025). "CCR7 expressed on CD103+ cDC1s is essential for tumor antigen drainage and T-cell activation." (PMID 41291775, 2025). "In a striatal tumor model, VEGF-C overexpression induces meningeal lymphangiogenesis, displaying a synergy effect with anti-PD-1/cytotoxic T-lymphocyte-associated protein 4 (CTLA-4) therapy, which can be abolished by CCL21/CCR7 blockade." (PMID 41511312, 2025). "It remains unclear how activated CCR7+ cDC in tumours differ from CCR7+ cDCs observed in the steady‐state or other inflammatory contexts." (PMID 40745918, 2025). "Knockout studies further revealed that CCR7 deletion significantly inhibited tumor growth, and the mechanism may involve the blockage of M2 polarization due to the upregulation of Dusp1 expression." (PMID 41445742, 2025).
tumor (continued). "Expression analysis of key regulators of cell migration (CXCR3, CCR7, CXCR5 and ITGAL, which encodes LFA1, an alias protein name) within these groups revealed significant upregulation of CCR7 in a subset of tumor-infiltrating SH2D2A-positive T cells and CXCR3 in infiltrating SH2D2A-positive T cells." (PMID 41394860, 2025). "Prior work suggests uptake of apoptotic cells may drive CCR7‐associated cDC1 activation programmes, while IRF1 and NF‐κB pathways have been more generally linked to cDC1 activation in tumours." (PMID 40745918, 2025). "CCR7 has long been established to be necessary for migration of cDC1s to LNs but has more recently also been suggested to be expressed in activated cDC1s that are retained in the tumours, potentially by CCL19‐expressing fibroblasts." (PMID 40745918, 2025). "Additionally, the transcription of CCR7 is upregulated by transcription factors, such as NF-κB and AP-1, which are activated by inflammatory cytokines produced in inflammatory sites and tumor microenvironment." (PMID 40028039, 2025). "Moreover, CCR7 was significantly higher expressed in epithelial cells of HCC tumor tissues, compared with paired adjacent normal liver tissues of HCC (p < 0.05, n = 10 patients)." (PMID 40685403, 2025). "CCL21 and CCL19 expressed in several stromal cells may exhibit antitumor activities at primary tumor sites because these chemokines induce the recruitment of CCR7-expressing activated dendritic cells to the tumor site." (PMID 40028039, 2025). "Besides, the infiltration of CCR7+ immune cells into the tumor sites through lymphatic vessels were also identified by immunofluorescent staining, such as CCR7+CD11b+, CCR7+CD68+and CCR7+CD3+ cells." (PMID 40685403, 2025). "Additionally, a subpopulation expressing FcγRI/CD64 with elevated CD40 and CCR7 levels—indicative of their role in T cell-mediated tumor immunity—is diminished." (PMID 40058234, 2025). "Tumor-resident CCR7+ dendritic cells (DCs) are key determinants of antitumor T cell responses." (PMID 41421339, 2025). "Furthermore, it was found that knockout CCR7 on HCC tumor cells inhibited the occurrence of EMT and the development of sorafenib resistance." (PMID 40685403, 2025). "Moreover, CCR7 facilitates lymph node metastasis by guiding tumor cell migration toward CCL21-expressing microenvironments and recruiting immunosuppressive Treg cells." (PMID 41462979, 2025). "In summary, our study reveals that the CCR7 signal may favor a pro- or anti-tumor function depending on where it is expressed in HCC." (PMID 40685403, 2025). "IL‐12p40 and CCR7 have also been shown to be important for cDC1‐mediated tumour rejection." (PMID 40745918, 2025). "Notably, CD19 CAR-T cells primarily exhibited the CD45RA + /CCR7 + phenotype characteristic of stem cell memory T cells (67.5 ± 4.9%), which are known for their potent and durable anti-tumor efficacy." (PMID 39891728, 2025). "In contrast, CCR7 and CCL19, which were negatively correlated with the risk score, play roles in immune cell homing and anti-tumor immunity, suggesting that their downregulation in the high-risk group may impair effective immune responses." (PMID 40464853, 2025). "First, the included studies showed variation in methodologies, including CCR7 expression categorization, tumor size cut-offs, and clinical staging criteria, which may contribute to inconsistencies and reduce the generalizability of our findings." (PMID 40299690, 2025). "Furthermore, in the context of immunotherapy, VEGF-C exerted anti-tumor effects through the infiltration of CCR7+ immune cells, enhancing the therapeutic efficacy of anti-PD-1 on HCC models." (PMID 40685403, 2025). "Notably, CD103N and CD103P cells from non-tumor and tumor tissues exhibited lower transcript levels of stemness markers, including CCR7, SELL, and TCF7, compared to circulating CD8+ T cells, resulting in lower stemness signature scores." (PMID 41182407, 2025).